MALAT1 (metastasis associated lung adenocarcinoma transcript 1)
Diseases named in the same sentence as MALAT1 in open-access papers (continued):
Sharing a sentence is not in itself a finding about the gene and the disease.
cancer (continued). "MALAT1 has been shown to bind polycomb repressive complex 2 (PRC2) components, which catalyze histone H3K27 methylation, and it plays an important role in transcriptional repression and cancer." (PMID 39725668, 2024). "Moreover, multiple studies have suggested key roles for lncRNAs MALAT1, LINC-PINT and NEAT1 in cancer, and in therapeutic resistance in breast cancer." (PMID 39199690, 2024). "As mentioned, MALAT-1 regulates EMT, metastasis, and chemoresistance in different cancers." (PMID 38201661, 2024). "In addition, metformin action on other types of cancers by regulating ten lncRNAs including AC006160.1, Loc100506691, lncRNA-AF085935, SNHG7, HULC, UCA1, H19, MALAT1, AFAP1-AS1, AC026904.1 is described." (PMID 36849958, 2023). "However, although MALAT1 is less expressed in TNBC, in these kind of cancers it plays crucial role in regulating the expression of key genes involved in tumour progression and metastasis." (PMID 37143733, 2023). "Moreover, MALAT1 can inhibit cancer cells apoptosis and thus stimulate metastasis, being activated in early NSCLC, and overexpression of MALAT1 is an early prognostic marker for patients." (PMID 38203731, 2023). "Oncogenic functions of certain cancer types seem to be dependent on MALAT1 expression, but not necessarily on MALAT1 upregulation." (PMID 37235843, 2023). "In colorectal cancer (CRC), suppression of MALAT1 restrained cell progression by downregulation of the expression of ABC, MDR1, MRP1, and breast cancer drug resistant proteins through targeting miR-20b-5p, resulting in drug resistance of cancer cells to 5-FU." (PMID 36829256, 2023). "What’s more, MALAT1 is reported to correlate with poor OS, RFS, DFS in various cancers." (PMID 37805491, 2023). "Overexpression of the lncRNA MALAT1 has been shown to promote the development of inflammation, as well as proliferation and invasion of tumor cells in the tumor microenvironment of EOC, ultimately resulting in the development of cancer." (PMID 37927399, 2023). "Unlike MALAT1, both MALAT1 and mascRNA are abundantly expressed and have cancer-promoting proportions; however, almost all LINC00478_FL RNA was cleaved after transcription." (PMID 36782197, 2023). "ExInAtor was modeled on 1112 whole genomes from 23 cancer types deposited in GENCODE, and predicted 15 lncRNA drivers with a high confidence, of which nine were novel lncRNAs and six were known cancer-related transcripts, including PCA3, MALAT1, BCAR4, lncRNA-ATB, and SAMMSON." (PMID 38068923, 2023). "Given the inhibitory effect of hsa-miR-429 on EMT, we speculate that HIF-1 tumor-specific impact on lncRNAs levels, e.g., MALAT1 or XIST, could potentially help cancer cells to overcome the hsa-miR-429-related blockaid and shift the cells towards EMT." (PMID 37296866, 2023). "The aim of the current study is to investigate if MALAT1 will give the same pattern of expression in TAMs of the hormonal, HER2+, and TNBC, highlighting that its role in cancer is still controversial whether it is an oncogenic or a tumor suppressor lncRNA." (PMID 36387279, 2022). "MALAT1, HOTAIR, H19, HOTTIP, ANRIL, and NEAT1 are among the most famous lncRNAs which have been mostly studied in many types of cancer exhibiting dysregulation in cancer cells, tissues and body fluids of affected patients." (PMID 35281110, 2022). "Furthermore, NEAT1, MALAT1, XIST, and PKD had reported or validated having a close relation with pro chemotherapy resistance of malignant tumors." (PMID 35873473, 2022). "In general, high levels of MALAT1 expression have been demonstrated in the vast majority of CRC specimens compared to adjacent non-tumor control colorectal tissue specimens in cancer patients." (PMID 35922756, 2022).
cancer (continued). "Importantly, miR-197-3p has been found to be sponged also by MALAT1 in NSCLC, contributing to the process of EMT and cancer cell resistance to treatment with cisplatin, adriamycin, gefitinib and paclitaxel." (PMID 35922756, 2022). "The functions of miR-330-5p and miR-330-3p in various types of cancer, not yet taking into account the interaction with MALAT1, have been discussed in a recent review article." (PMID 35922756, 2022). "We also checked the cancer stem cell markers, Sox2 and Nanog in both of these CTCL cells and observed that both the markers, that we evaluated, were significantly reduced upon silencing of MALAT1 in HH as well as in H9 cells." (PMID 36059695, 2022). "Thus, MALAT1 can regulate the miR-206-induced PI3K/Akt signaling pathway and promote cancer cell proliferation through sponge adsorption." (PMID 36419933, 2022). "Thus, by repressing the CDH1 gene and sponging the miR-218-5p, MALAT1 can promote the EMT process and cancer cell metastasis, lead to an increase in Survivin levels and cancer cell resistance to 5FU and oxaliplatin treatment." (PMID 35922756, 2022). "When analyzing the Receiver operating characteristic (ROC) curves for these genes we noted that, for the comparison of normal to cancer samples, MEG3 and MALAT1 had the highest Area Under the Curve (AUC), while when comparing normal vs. CIN, MLH1 and DAPK1 presented the highest AUC." (PMID 35682732, 2022). "The effects of MALAT1 suppression and BET inhibitor JQ1 on the malignant phenotypes and cancer stem cell- (CSC-) like properties of laryngocarcinoma cells as well as the expression of bromodomain-containing protein 4 (BRD4), YAP1, and EMT markers were investigated." (PMID 35601153, 2022). "Both MALAT1 and HOTAIR have been proposed as therapeutic targets in cancer." (PMID 36233046, 2022). "Therefore, lncRNAs, such as MALAT1, UBE2CP3, HULC, UCA1, and PCA3 play an essential role in cancer metastasis by altering gene expression." (PMID 33805687, 2021). "The silencing of MALAT1 resulted in low cell proliferation of SKOV3 and A2780 cancer cells." (PMID 34204094, 2021). "The link between MALAT1 and EMT was documented in various cancer in multiple mechanisms." (PMID 34769245, 2021). "Several similar works were found in recent studies however, there was no report about the comprehensive analysis of MALAT1 across various cancers by multiple databases." (PMID 34308750, 2021). "Their high specificity allows for the detection of cancer initiation (e.g., SPRY4-IT1), progression (e.g., ATB), metastasis (e.g., LINC00461, CCAT2 and H19) and response to therapy (e.g., MALAT1 or HOTAIR)." (PMID 34072257, 2021). "MALAT1 may act as a potential therapeutic target and molecular biomarker in HCC, which regulates the proliferation, metastasis, cancer cell metabolism as well as the stemness of Hepatic CSCs via multiple mechanisms." (PMID 34690755, 2021). "For example, MALAT1, which is highly expressed in most cancers, regulates the cell cycle, and PCA3 is an important molecular marker in the early stage of cancer." (PMID 34079798, 2021). "Interestingly, exosomes from the PTC cancer stem cell (PTC-CSC) model were transferred beside the transcription factors SLUG and SOX2, the lncRNA MALAT1, and the linc-ROR resulting to the induction of EMT." (PMID 35186709, 2021). "Other lncRNAs such as HOTAIR, MALAT1, and GAS5 also show promise as cancer biomarkers." (PMID 33799946, 2021). "3D cultured cells were also shown to have lower levels of genes related to cell proliferation or mitosis (CCNA2, MKI67, and BUB1) and differentiation (ESR1) relative 2D cultured, consistent with higher levels of a cell cycle inhibitor (CDKN1) and cancer stemness–related markers (CD44 and MALAT1)." (PMID 34869246, 2021). "A study on the mechanism of exosomal MALAT1 activity revealed that it can possibly stimulate the expression of angiogenesis-related genes, including VEGF-A, VEGF-D, and angiogenin, thereby facilitating cancer angiogenesis." (PMID 34819615, 2021).
cancer (continued). "However, genes associated with cell differentiation (EPCAM, CK8, CK18, and FOXA2), EMT (SNAI1, FOSL1, and ID1), and cancer stem cells (CD44, CD133, ETV1, MALAT1, NEAT1, and NESTIN) displayed a more varied response compared to 2D cells." (PMID 33356003, 2021). "Many of the well-studied lncRNAs, that are considered as regulatory molecules with various significant functions in cancer, have no junctions in their sequences such as MALAT1, NKILA, NEAT1 and NORAD." (PMID 34202021, 2021). "While increased expression of MALAT1 has been correlated with cancer or severe cancer phenotypes, how the roles of MALAT1 are influenced by its myriad structural elements is not yet clear." (PMID 33450947, 2021). "Finally, meta-analysis of transcriptomic datasets has also shown MALAT1 to be upregulated in several cancer tissues such as lung, CRC, prostate, breast, etc. cancer compared to normal tissues." (PMID 32503170, 2020). "The intersection set of the two gene lists includes 5 lncRNAs (EIF1AX-AS1, LINC00115, LINC01237, MALAT1 and LINC00528), among which only LINC00115 and MALAT1 have been experimentally validated to correlate with cancers according to the lncRNADisease2.0 database." (PMID 33318305, 2020). "Knockout of MALAT1 induced G2/M cell cycle arrest, inhibition of epithelial-mesenchymal transition (EMT), decreased cancer stem cell-like properties, repressed N-myc downregulated gene-1 (NORG-1) and hindered the growth and invasion of cancer cells." (PMID 32257946, 2020). "It is noteworthy that no hCIS was found to overlap MALAT1 despite its being amongst the most widely-studied cancer lncRNAs14." (PMID 32024996, 2020). "The upregulation of MALAT1 in cancer cells compared to the non-malignant cells was described in different types of primary tumors and also cancer cell lines derived from various tissues." (PMID 32369931, 2020). "Investigating the role of lncRNAs in cellular metabolism, particularly that of MALAT1, which exerts essential regulatory functions on the TCA cycle, may lead to the development of novel strategies to treat cancer." (PMID 33375130, 2020). "Indeed, circulating HOTAIR, MALAT1, and MEG3 transcripts were found significantly higher in cancer patients compared to healthy subjects suggesting their potential as diagnostic biomarkers." (PMID 32154165, 2020). "Fan Y. and colleagues illustrate that TGF-β overexpression in the tumor microenvironment could induce cancer metastasis through EMT regulation and validate MALAT1 as an important mediator of TGF-β related EMT." (PMID 33123473, 2020). "In a preclinical setting, lncRNAs have been suggested as potential diagnostic or prognostic biomarkers affecting a variety of tissues including the heart (MALAT1), reproductive system (H19), muscle (linc‐MD1), and several cancer types (MALAT1, H19, MEG3, HOTAIR) (reviewed in 81, 82)." (PMID 32100288, 2020). "The most prolific lncRNAs, with ≥16 recorded cancer types, are HOTAIR, MALAT1, MEG3 and H19." (PMID 32024996, 2020). "Consistent with our hypothesis, we found elevated MALAT1 levels in HCC samples and cells that correlated with more advanced cancers." (PMID 31777593, 2019). "Functionally, MALAT1 promotes EZH2 occupancy and increases H3K27 trimethylation level at Polycomb target loci, thereby enhances EZH2-mediated gene repression, cell invasion and migration of cancer cells." (PMID 30788509, 2019). "lncRNA MALAT1 was also positively correlated with SSV breakpoints, though likely not representing an oncogene itself but rather a correlate of aggressive cancers." (PMID 31610796, 2019). "Moreover, MALAT-1 can be a blood based biomarker for NSCLC as it is detectable and increased in peripheral human blood sample from patients compared to cancer-free controls." (PMID 30012957, 2018). "Several cancer related pathways such as epithelial mesenchymal transition (EMT) and DNA replication were enriched, which implies that MALAT1 sub-networks might be involved in the metastasis related pathways." (PMID 30367572, 2018).
cancer (continued). "Likewise, a lot of previous meta-analyses investigated the relationship between the other lncRNAs expression and prognosis of corresponding cancers, such as HOTAIR, H19 and MALAT1." (PMID 29805767, 2018). "Unlike most of lncRNAs, MALAT1 is particularly abundant, highly conserved and ubiquitously expressed in multiple types of cancer." (PMID 30093838, 2018). "Additionally, HOTAIR, MALAT1, H9 and GAS5 have been reported as prognostic markers in the plasma of cancer patients." (PMID 28872613, 2017). "Previous studies have found that MALAT1 is significantly highly expressed in non–small cell lung carcinoma (NSCLC) patients and regulates invasion, migration, and tumor growth in many other cancer types." (PMID 29237426, 2017). "In recent years, a large amount of studies proved that abnormal expression of lncRNAs such as H19, MALAT1, HOTAIR, PVT1, may contribute to cancer development." (PMID 28938549, 2017). "The lncRNAs have been proved to engage in cancer metastasis such as HOTAIR, MALAT1 and HULC." (PMID 28969031, 2017). "Furthermore, lncRNAs such as MALAT1, HOTAIR, and H19 were found to act as tumor suppressor genes or oncogenes in cancer development." (PMID 28146578, 2017). "In addition, the overrepresentation of cell cycle-, cancer-, proliferation- and B-MYB-related gene sets corresponds to the validated MALAT1 functionality reported in the literature." (PMID 29220434, 2017). "MALAT1, HOTAIR...) have been described in detail for several cancer entities." (PMID 28270163, 2017). "Our current study investigated lncRNA, miRNA, and protein-coding genes and found that MALAT1, miR-320a, and FOXM1 could form a gene signaling pathway to regulate HUVEC proliferation, which may provide a novel strategy for future control of cancer progression." (PMID 28977880, 2017). "MiR-101 and miR-217 are functionally involved in several cancers as tumor suppressors and exhibited a significant negative correlation with MALAT1 in ESCC tissue samples and adjacent normal tissues." (PMID 29147648, 2017). "We believed that more clinical studies should be conducted to evaluate potential prognostic role of MALAT1 in other types of cancer that have not been included." (PMID 27777857, 2016). "Results indicated that these treatments had no any effects on serum levels of MEG3, SNHG16 and MALAT1, which provides a base for cancer diagnosis as the useful and stable biomarkers." (PMID 27793008, 2016). "Activation of MALAT1 by gene amplification seems unlikely because MALAT1 is located in a chromosomal region (11q13.1) not recurrently amplified in human cancers." (PMID 27172249, 2016). "It was suggested that elevated MALAT1 expression predicted a poor outcome for OS in 12 types of cancers (pooled HR = 1.91, 95 % CI 1.49–2.34) with no heterogeneity (I2 = 0.0 %, P = 0.728)." (PMID 27777857, 2016). "We searched PubMed, EmBase, Web of Science, Cochrane Library, and OVID to address the level of MALAT-1 expression in cancer cases and noncancerous controls (accessed February 2015)." (PMID 26989678, 2016). "The MALAT1 expression level was notably higher in cancer tissues compared with that in matched adjacent non-cancerous tissues (P=0.0011)." (PMID 27015363, 2016). "MALAT1 and HOTAIR are both examples of lncRNAs which are deregulated in the majority of cancers." (PMID 26516918, 2015). "MALAT1 could be detected in peripheral blood, showing different expression levels between NSCLC patients and cancer-free controls." (PMID 24313945, 2013). "Notably, a negative correlation of MALAT1 with M1 macrophages was observed across all cancers in which it was involved, while a positive correlation with CD4+ Tcm cells was observed." (PMID 40728857, 2025).
cancer (continued). "Our results highlight the importance of three novel positive circuits—CricNOTCH1/miR-34c/Myc, lncRNA MALAT1/miR-34a/Myc, and Myc/xCT—which have not been extensively explored in prior studies but are predicted to play significant roles in regulating cancer cell fate decisions." (PMID 39846637, 2025). "The role of MALAT1, a lncRNA, in cancer progression is not yet fully understood." (PMID 39256366, 2024). "Employing various mechanisms of action, MALAT1 modulates multiple cellular pathways (such as MAPK/ERK, PI3K/AKT, β-catenin/Wnt, Hippo-YAP, VEGF, NF-κB, etc.)which regulate proliferation, apoptosis, communication with the microenvironment, and other cancer-related processes." (PMID 38255996, 2024). "Importantly, MALAT-1 stimulates cell proliferation, migration, and metastasis and serves a vital role in driving the epithelial-to-mesenchymal transition (EMT), subsequently acquiring cancer stem cell-like properties and developing drug resistance." (PMID 38201661, 2024). "In addition, cancer cells in SN upregulated MT-RNR2, DST, and MALAT1." (PMID 37745301, 2023). "LncRNA MALAT1 enhances tumor metastasis in most but not all types of cancers." (PMID 35475470, 2022). "MALAT1 was significantly co-expressed with various signatures of genes involved in HCC progression, including the cell cycle, DNA damage repair, mismatch repair, homologous recombination, molecular cancer m6A, exosome, ferroptosis, infiltration of lymphocyte (p < 0.05)." (PMID 36685103, 2022). "Although the absence of MALAT1 is sustained by cells in normal development, its elevated levels in cancer settings may contribute to the deregulation of cancer-specific pathways." (PMID 36230680, 2022). "It is worth mentioning here that the upregulation of MALAT1 through miR-200c-3p sponging leads to an increase in the level of the transcriptional repressor ZEB1 and contributes to the promotion of the EMT process, and thus the migration and invasiveness of cancer cells." (PMID 35922756, 2022). "In view of the controversy surrounding the oncogenic vs. tumor suppressor role of MALAT1 in human cancers, we started with the quantitation of CTCL in serum of CTCL patients in our cohort and we further employed CTCL cell lines HH and H9 to further characterize the role of MALAT1 in CTCL." (PMID 36059695, 2022). "Of course, MALAT1 may also function in HCC through other mechanisms, and we cannot exclude the possibility that the functional module reported here may play roles in other types of human cancers as well." (PMID 36563164, 2022). "However, Malat1 knockout mice do not appear to have an apparent cancer phenotype but instead display defects in the immune response when exposed to multiple pathogens." (PMID 35681513, 2022). "At present, there is no report on the cancer-promoting effect of lncRNA MALAT1 on MPM." (PMID 34761116, 2021). "Hence, collectively, MALAT1 may form a positive bidirectional circuit with oncoprotein YAP in the regulation of cancer development and tumorigenesis in a cancer tissue‐specific manner." (PMID 32779318, 2020). "However, the exact role of MALAT1 on wound healing has not been clearly identified despite its extensive investigation in the cancer." (PMID 32342982, 2020). "Having the knowledge that MALAT1 was upregulated in cancer tissues, we asked whether non-cancerous tissues would increase MALAT1 / TALAM1 expression after a signal driving migration." (PMID 31382922, 2019). "The depleted in breast cancer 1 (DBC1) was identified through stable isotope labeling by amino acids in cell culture (SILAC) quantitative proteomic analysis, RIP, RNA pull-down, and WB assays, thus confirming that MALAT1 physically interacts with the aa120-280 region of DBC1." (PMID 31717266, 2019). "Pterostilbene did not inhibit HOTAIR, MALAT1 or BISPR in MCF7 cancer cells." (PMID 30619763, 2018).